CCL20 (C-C motif chemokine ligand 20)
Diseases named in the same sentence as CCL20 in open-access papers (continued):
Sharing a sentence is not in itself a finding about the gene and the disease.
lung carcinoma (69 papers, 2011 to 2025). "For example, the expression of CCL20 in lung cancer cells is higher in patients with advanced lung cancer than in patients with early-stage lung cancer, and this high expression is associated with a poor prognosis." (PMID 32019546, 2020). "For example, CCL20 is induced by another important carcinogen in tobacco smoke, nicotine-derived nitrosaminoketone, and is overexpressed in smoker lung cancers and inversely associated with prognosis." (PMID 26565418, 2015). "Another tobacco carcinogen NNK (4-(methylnitrosamino)-1-(3-pyridyl)-1-butanone) also induces CCL20 production via activation of NF-κB pathway, highlighting the complicated actions and mechanisms underlying tobacco smoke in inducing lung cancer." (PMID 39042313, 2024). "Similarly, CCL20, a crucial chemoattractant linked to inflammatory cell recruitment, displayed overexpression, which can promote lung cancer cell migration, proliferation and CD8+ T‐cell recruitment." (PMID 38445456, 2024). "The metabolites of nicotine, NNK, and PAHs are related to lung cancer, and a chemokine CCL20 may also be associated with lung cancer risk in smokers." (PMID 27322209, 2016). "Moreover, tobacco smoking possess the major risk factor for lung cancer and may be responsible for up-regulation of CCL20 expression at both mRNA and protein levels." (PMID 37316552, 2023). "Integrated analysis of scRNA-seq data from human lung cancer tissues revealed that macrophages displayed marked enrichment of CCL20 transcripts, exhibiting higher expression levels compared with other cell subsets." (PMID 41055972, 2025). "In lung cancer, CCL20 is highly expressed and promotes cell migration and proliferation via autocrine signaling, highlighting its oncogenic role in tumor progression." (PMID 40444282, 2025). "The engineering of CCR6, the receptor for CCL20, within epidermal growth factor receptor (EGFR)-targeting CAR-T cells led to improved trafficking, penetration, and clearance of solid tumors in a CCL20+ lung cancer xenograft mouse model." (PMID 38217016, 2024). "In this study, we found that activation of PD-L2/RGMB pathway increased CCL20 expression to promote lung cancer progression." (PMID 39042313, 2024). "Some studies have found that IL-17A promotes the secretion of CCL20 by cancerous cells, implicating the CCL20/CCR6/IL-17 axis as a potential new therapeutic target for lung cancer." (PMID 39906741, 2024). "Autophagy induced by TLR4 or TLR3 activation augments the production of various cytokines such as IL6, CCL2/MCP-1, CCL20/MIP-3α, and VEGFA by promoting TNF receptor-associated factor 6 ubiquitination, which ultimately drives lung cancer progression." (PMID 37484013, 2023). "CCL20 can promote lung cancer cell proliferation and migration by activating the ERK and PI3K signaling pathways." (PMID 36164607, 2022). "Several studies have shown that overexpression of CCL20 increases the migration and proliferation of lung cancer cells through the PI3K pathway." (PMID 36231045, 2022). "We also found a novel macrophage subtype M_C3_CCL20 in lung cancer by IE-guided analysis, and cells of M_C3_CCL20 were related with worse prognostic outcomes in lung cancer (LUAD and LUSC)." (PMID 35102420, 2022). "It has been documented that CCL20 production from lung cancer inflammatory microenvironment, by activation PI3K signaling pathway, led to the boosting of the cell migration and proliferation of NSCLC cell lines." (PMID 35719962, 2022). "CCL20 levels are elevated in many cancer types such as breast, liver, and pancreatic cancers, but are low in adrenal gland and lung cancers." (PMID 36387204, 2022). "For instance, the high expression of MMP14 and CCL20 facilitates the cancer cell proliferation and metastasis of lung carcinoma." (PMID 35372503, 2022). "CCL20 is a family of secreted proteins in immune regulation and inflammatory processes, and promotes the migration and proliferation of lung cancer cells." (PMID 35910766, 2022).
lung carcinoma (continued). "Compared with healthy controls, the levels of CXCL14, CXCL13 and CCL20 were increased in the plasma of patients with lung cancer." (PMID 35769715, 2022). "Overexpression of CCL20 promoted the induction of the lung cancer cell migration and proliferation through PI3K pathway." (PMID 34580602, 2021). "proved that the increasing secretion of IGF-1 and CCL20 promotes brain metastasis of lung cancer cells by polarizing microglia and suppressing innate immune function." (PMID 34804946, 2021). "In patients with NSCLC, the CCL20 gene and protein are overexpressed, and autocrine of CCL20 can promote the migration and proliferation of lung cancer cells." (PMID 34881236, 2021). "Knockdown of lncRNA-u50535 decreases lung cancer cell proliferation and migration, induces G0/G1 phase arrest, and promotes cell apoptosis with decreased CCL20, CCR6, and phosphorylated ERK (pERK) levels." (PMID 32707869, 2020). "Adrenal glands have a high expression of the chemokine CCL20, whereas lung cancer cells frequently express its ligand CCR6, possibly explaining the frequency of adrenal metastases from lung cancer." (PMID 30328287, 2018). "It was found that patients developed the adrenal metastasis after resections of primary NSCLC and had high levels of CCL20 in adrenal glands responsible for the selective recruitment of CCR6‐expressing cancer cells from the lung cancer." (PMID 26968871, 2016). "CCL20 promoted lung cancer cells migration and proliferation in an autocrine manner via activation of ERK1/2‐MAPK and PI3K pathways." (PMID 26968871, 2016). "Interleukin (IL)‐1β was used in this study to stimulate CCL20 production from lung cancer cells and activate signalling pathways of MAPK and PI3K." (PMID 26968871, 2016). "About 80% of patients with NSCLC had the overexpression of CCL20 proteins in the lung cancer tissue." (PMID 26968871, 2016). "The expression of CCL20 mRNA and protein isolated from the lung cancer tissue was significantly higher than that from the normal lung tissue (P < 0.05), respectively." (PMID 26968871, 2016). "This study aimed at investigating potential mechanisms of CCL20 function and production in human non‐small cell lung cancer (NSCLC)." (PMID 26968871, 2016). "Nicotine-derived nitrosamino ketone (NNK) could promote lung cancer formation by upregulating the chemokine CCL20." (PMID 38434974, 2024). "While these findings suggest that MIA3 and CCL20 may be crucial in mechanisms through which T cells promote brain and bone metastasis in lung cancer, additional research is needed for confirmation." (PMID 38445456, 2024). "One study showed that IL-1β induced signaling pathway can directly stimulate the production of CCL20 in lung cancer cells, and activate MAPK and PI3K signaling pathways through its autocrine, which has a positive effect on the progression and invasion of cancer cells in lung tissue." (PMID 36447119, 2023). "Production of CCL20 from lung cancer cells induces the cell migration and proliferation." (PMID 36313444, 2022). "For instance, it has been shown that tobacco smoke could induce the production of chemokine CCL20 and promote lung cancer progression." (PMID 35719962, 2022). "CCL20 has the potential to become a new therapeutic target for lung cancer." (PMID 35437508, 2022). "CCL20 belongs to the chemokine family and promotes lung cancer cell migration and proliferation." (PMID 36497225, 2022). "CCL20, a member of CC chemokines, has been observed to mediate the migration of inflammatory cells, thereby involving in metastasis of cancer, including colorectal, pancreatic, or lung cancer." (PMID 34787244, 2021). "Our results may provide a novel evidence that CCL20 could be a new therapeutic target for lung cancer." (PMID 26968871, 2016). "This study provided solid evidence that CCL20 overexpressed in human lung cancer tissues and cells, which may act as the initiator for the secondary inflammatory responses in the development of the cancer microenvironment." (PMID 26968871, 2016).
lung carcinoma (continued). "Previous findings demonstrated that CCL20 could be overexpressed and overproduced by lung cancer cells." (PMID 26968871, 2016). "Our results indicate that lung cancer cells may produce CCL20 in autocrine and paracrine manners to attract tumour‐associated macrophages and tumour cells." (PMID 26968871, 2016). "Of those intracellular signal pathways, the MAPK‐PI3K pathway in lung cancer cells might play the independent and necessary role in the regulation of CCL20 production during the formation of inflammatory microenvironment." (PMID 26968871, 2016). "This study aimed to evaluate the hypothesis that lung cancer cells per se may secrete CCL20 to chemoattract the infiltration of inflammatory cells to the tumour tissue, responsible for the development of tumour inflammatory microenvironment." (PMID 26968871, 2016). "MAPK and phosphoinositide‐3‐kinas (PI3K) signalling pathways may be involved in CCL20 production in lung cancer." (PMID 26968871, 2016). "The increased production of CCL20 from adrenal glands might contribute to the selective recruitment of CCR6‐expressing cancer cells in lung cancer 12, although the mechanism by which CCL20 is involved in the formation of lung cancer remains unclear." (PMID 26968871, 2016). "Smokers with lung cancer have increased serum CCL20 levels, an inflammatory molecule shown to promote tumor cell proliferation and migration, that has also been significantly correlated with advanced disease and poor prognosis in lung cancer." (PMID 27784305, 2016). "CCL20 promotes lung cancer cell proliferation and migration." (PMID 26565418, 2015). "Macrophage inflammatory protein-3 (MIP-3α), also known as CCL20, has been linked to the propagation of several malignancies, including prostate, hepatic and pancreatic carcinomas, raising the possibility that MIP-3α plays a role in lung carcinogenesis, thereby affecting the prognosis of lung cancer." (PMID 25013520, 2014). "The increase of metastatic potential of CCR6-expressing lung cancer cells may result from a decrease in local production of CCL20 by the tumor cells themselves (and possibly also by stromal cells), which facilitates migration of tumor cells away from their original site." (PMID 37316552, 2023). "In addition, CCL20 was upregulated in patients with relapsed lung cancer and could accelerate cell proliferation through the ERK signaling pathway." (PMID 35719915, 2022). "A newly published paper demonstrated that CCL20 could facilitate the recruitment and activation of type 3 innate lymphoid cells and thus promote antitumor immunity and enhance tumor sensitivity to immunotherapy in lung cancer." (PMID 36614059, 2022). "Expression of lncRNA-u50535 is upregulated in lung cancer tissues and cell lines compared with normal tissues and cells, and Western blot and luciferase reporter gene assays have demonstrated that lncRNA-u50535 has also increased the translation and transcription of CCL20 in lung cancer cells." (PMID 32707869, 2020). "Our data indicated that IL‐1β could stimulate CCL20 production from lung cancer cells through the activation of MAPKs and PI3K signal pathways, and the auto‐secretion of CCL20 could promote lung cancer cell migration and proliferation through the activation of ERK and PI3K signal pathways." (PMID 26968871, 2016). "Western blotting and qRT-PCR analyses were performed to quantify the expression levels of HER2, CXCL13, and CCL20 in the normal bronchial epithelial cell line BEAS-2B and several lung cancer cell lines (PC9, A549, H1734, H1975, H1299, and HCC827)." (PMID 40764989, 2025). "Cochrane’s Q test did not provide evidence of heterogeneity between CCL14 (p = 0.916), CCL19 (p = 0.446), CCL20 (p = 0.130), CCL21 (p = 0.878), CCL27 (p = 0.762), CXCL9 (p = 0.340) and CXCL13 (p = 0.770) and lung cancer." (PMID 38075694, 2023).
lung carcinoma (continued). "The engagement of TLR3/4 was reported to induce increases in the production of IL-6, CCL2, CCL20, VEGF, and MMP2 through NF-κB activation, thereby enhancing lung cancer migration and invasion." (PMID 37287005, 2023). "The engagement of TLRs induced NF-κB activation via the TRAF6-TAK1 signaling axis and increases in the production of IL-6, CCL2, CCL20, vascular endothelial growth factor (VEGF), and MMP2, thereby enhancing lung cancer migration and invasion." (PMID 37287005, 2023). "Autophagy induced by TLR4 or TLR3 activation can enhance the production of cytokines such as IL-6, CCL2, MMP2, and CCL20 by promoting TRAF6 ubiquitination, thus facilitating the migration and invasion of lung cancer cells." (PMID 35422093, 2022). "Previous reports have demonstrated that TLR3/4 activation can increase the production of IL-6, CCL2, MMP2, and CCL20 cytokines by promoting TRAF6 ubiquitination and autophagy induction, thereby facilitating the migration and invasion of lung cancer cells." (PMID 35422093, 2022). "The CCL20 was expressed in cancer cells and macrophages in lung cancer tissues, while the CXCL12 was expressed by fibroblasts in lung cancer tissues." (PMID 35069521, 2021). "In lung cancer, CCL20-mediated MEK signaling was shown to mediate proliferation and migration, while in breast cancer CCL20-mediated MEK signaling was shown to mediate proliferation." (PMID 34853656, 2021). "The production of CCL20 has been reported to activate MAPK and PI3K signaling pathways following IL-1β treatment of lung cancer cells." (PMID 32418112, 2020). "It has been previously reported that TLR4-induced autophagy activation promoted migration and invasion of lung cancer by induction of chemokines and immunosuppressive factors including CCL2, CCL20, IL-6, VEGFA, and MMP2." (PMID 32384667, 2020). "A previous study demonstrated that CCL20/CCR6 are involved in the metastasis of a variety of tumors, including prostate, colorectal and lung cancer." (PMID 29788995, 2018). "Therefore, CCL20, which is up‐regulated in response to inflammatory stimuli, may have an important role in the development and progression of inflammatory microenvironment in lung cancer." (PMID 26968871, 2016). "For instance, the SAA1 lung cancer biomarker, neuro-inflammation factor MMP1, the chemokine ligands (C-C motifs) CCL2, CCL5, and CCL20, and cytokines such as IL6, IL8, IL16, were all significantly modulated." (PMID 26950733, 2016). "To test the potential pro-carcinogenic effects of CCL20 and CCR6 in lung cancer, we first aimed to characterize the expression and tissue localization of this chemokine/chemokine receptor pair in NSCLC tumors." (PMID 21949768, 2011). "Using lung cancer, melanoma, and colon cancer mouse models, ADAR1 secretion in macrophages contributed to the establishment of immunosuppressive tumor microenvironment via CCL20-mediated angiogenesis and antitumor suppression." (PMID 39985603, 2025). "Notably, all lung cancer cell lines exhibited elevated protein expression of CXCL13 and CCL20, with CXCL13 being approximately three times higher in H1975, H1299, and HCC827, and CCL20 being more than twice as high in A549, H1734, H1975, and HCC827." (PMID 40764989, 2025). "It was revealed the chemokine CCL20, which specifically bind to CCR6 plays a significant role in development of NSCLC by regulation of lung cancer cell proliferation, apoptosis, migration, EMT, as well as they are involving in modification of the immune response to cancer." (PMID 37316552, 2023). "Also in our study was proved a change in the expression of CCL20 and CCR6 mRNA in lung cancer tissue." (PMID 37316552, 2023). "In the lung carcinoma syngeneic model, we confirmed that RORγt agonist treatment increased intratumoral CD8+ T cells and MoDCs through the promotion of CXCL10 as well as promotion of Type 17 T cell migration via upregulation of CCL20 and CCR6 expression." (PMID 35459193, 2022).
lung carcinoma (continued). "In addition, a recent study also identified that CCL19, CCL20, and CXCL13 are highly expressed in lung cancer, and subsequent co-expression of CCL20 receptor CCR6 in CAR-T increased cell migration and tumor killing." (PMID 34553036, 2021). "Moreover, stimulation with TLR4 and TLR3 can induce the production of IL-6, CCL2/MCP-1, CCL20/MIP-3α, VEGFA (vascular endothelial growth factor A), and MMP2 known to play pivotal roles in the migration and invasion of lung cancer cells through induction of autophagy." (PMID 37443143, 2023). "A higher CCR6 and CCL20 mRNA expression level was observed in the AC group compared to the SCC group, which may be responsible for stronger biological aggressiveness of this histopathological type of lung cancer." (PMID 37316552, 2023). "Additionally, CCL20 and CXCL10 play major roles in the growth, migration and metastatic capabilities of lung cancer cells and were shown to decrease immunogenicity against cancer cells through recruitment of inflammatory immune cells, leading to decreased patient survival." (PMID 31001473, 2019). "Additionally, activation of TLR4 and TLR3 stimulated autophagy induction in lung cancer cells and induced enhancements of cytokine productions, such as IL-6, CCL2/MCP-1, CCL20/MIP-3α, VEGFA, and MMP2, by encouraging TRAF6 ubiquitination, thereby led to increases of cell migration and invasion." (PMID 31620128, 2019). "Interleukin‐1β could directly stimulate CCL20 production of lung cancer cells through the activation of MAPKs and PI3K signal pathways, and the auto‐secretion of CCL20 could promote lung cancer cells migration and proliferation through the activation of ERK and PI3K signal pathways." (PMID 26968871, 2016). "Although CCL20 is known to induce ERK1/2 signaling in lung cancer cells 43, we did not observed the attenuation of ERK1/2 signaling following knockdown of CCL20 in PC cell lines, suggesting that CCL20 signaling might activate differential downstream signaling dependent in specific cancer types." (PMID 33123272, 2020).